UCP3 (uncoupling protein 3)
Description:
Putative transmembrane transporter that plays a role in mitochondrial metabolism via an as yet unclear mechanism. Originally, this mitochondrial protein was thought to act as a proton transmembrane transporter from the mitochondrial intermembrane space into the matrix, causing proton leaks through the inner mitochondrial membrane, thereby uncoupling mitochondrial membrane potential generation from ATP synthesis. However, this function is controversial and uncoupling may not be the function, or at least not the main function, but rather a consequence of more conventional metabolite transporter activity.
Synonyms: SLC25A9
Tractability: Antibody: UniProt predicts a signal peptide or a membrane-spanning region; the Human Protein Atlas places it where antibodies can reach.
Gene: Protein-coding gene on chromosome 11 (74,000,277 to 74,009,085, reverse strand). Ensembl gene ENSG00000175564.
Subcellular location: Mitochondrion inner membrane
Subcellular location (Human Protein Atlas): Cytosol; Nucleoplasm; Plasma membrane
Pathways (Reactome):
Metabolism: The fatty acid cycling model
Gene Ontology:
Molecular function: calcium ion transmembrane transporter activity; oxidative phosphorylation uncoupler activity; protein binding; proton transmembrane transporter activity
Biological process: proton transmembrane transport; adaptive thermogenesis; lipid metabolic process; mitochondrial transmembrane transport; positive regulation of cold-induced thermogenesis; respiratory gaseous exchange by respiratory system; response to cold; cellular response to hormone stimulus; lipid hydroperoxide transport; response to activity; response to fenofibrate; response to glucocorticoid; response to hypoxia; response to insulin; response to nutrient; response to steroid hormone; response to superoxide; transmembrane transport
Cellular component: mitochondrion; mitochondrial inner membrane
Genetic constraint (gnomAD): Loss-of-function variants: 24 observed, 28.14 expected, observed/expected ratio (o/e) 0.85, 90% interval 0.62 to 1.2. The upper end of that interval is the gene's LOEUF score, 1.2, which puts it in group 5 of 6, group 1 being the genes least tolerant of losing a copy. Missense variants: 397 observed, 438.17 expected, observed/expected ratio (o/e) 0.91, 90% interval 0.83 to 0.98. Synonymous variants: 184 observed, 177.16 expected, observed/expected ratio (o/e) 1.04, 90% interval 0.92 to 1.17.
Homologues: Orthologues: chimpanzee UCP3 (99% identical), macaque UCP3 (96% identical), dog UCP3 (92% identical), pig UCP3 (89% identical), rabbit UCP3 (88% identical), guinea pig UCP3 (87% identical), mouse Ucp3 (86% identical), rat Ucp3 (86% identical), tropical clawed frog ucp3 (71% identical). Paralogues in human: UCP2 (72% identical), UCP1 (57% identical), SLC25A30 (36% identical), SLC25A14 (36% identical), SLC25A27 (34% identical), SLC25A12 (30% identical), SLC25A13 (29% identical), SLC25A34 (28% identical), SLC25A1 (28% identical), SLC25A47 (27% identical), SLC25A22 (26% identical), SLC25A10 (26% identical), and 37 more.
Diseases named in the same sentence as UCP3 in open-access papers:
UCP3 is named in the same sentence as 73 diseases in open-access papers, as found by Europe PMC text mining. Sharing a sentence is not in itself a finding about the gene and the disease. The quoted sentences say what the papers report.
Obesity (81 papers, 2005 to 2026). Accumulation of substantial excess body fat. "The -55C/T polymorphism in the UCP3 promoter has been shown to increase gene expression and resting energy expenditure, thereby enhancing aerobic potential and reducing obesity risk." (PMID 41300761, 2025). "Studies have revealed that upregulation of UCP2 and UCP3 due to increased elevation of free fatty acids and mitochondrial ROS generation, as well as in the case of advanced obesity, caused cell death and heart seizure." (PMID 34828008, 2021). "On the other hand, carriers of a −55C > T mutation in the UCP-3 gene have a reduced risk for obesity but only if they have a high physical activity status." (PMID 33833685, 2021). "It has been recently discovered that there is a close association between UCP3 ablation and fat accumulation in mice exposed to a high-fat diet, reflecting a protective role for this gene against obesity." (PMID 32595696, 2020). "Our results demonstrate that myocardial UCP3 deficiency is a common feature of rodents with obesity, insulin resistance and type 2 diabetes, and is linked to the hyperinsulinemic state of the animals." (PMID 30374710, 2018). "Because obesity and diabetes are associated with an increased supply of circulating fatty acids to the heart, myocardial UCP3 levels should increase under those conditions." (PMID 30374710, 2018). "Genetic variants in the UCP2/UCP3 cluster have been considered candidate markers for obesity, diabetes, and fat metabolism in humans." (PMID 28615046, 2017). "Human Polymorphisms in the UCP3 gene also suggest an impact of UCP3 on fat metabolism, obesity, and T2DM." (PMID 25713540, 2015). "A recent meta-analysis demonstrates an association between the -55C/T polymorphism in the UCP-3 gene and obesity further suggesting such a UCP-3 function." (PMID 26304588, 2015). "Based on genetic association studies, UCP2, UCP3, or both are reportedly associated with obesity, insulin resistance, type 2 diabetes mellitus, and metabolic syndrome in humans." (PMID 25495519, 2014). "These are the reasons why the roles played by UCP1-3826A/G, UCP2-866G/A, UCP2 Ala55Val, UCP2 Ins/Del and UCP3-55C/T polymorphisms in obesity risk and BMI changes have been extensively studied, although the results of these associations are still inconclusive." (PMID 24804925, 2014). "Genetic association studies have shown that human UCP2 and UCP3 variants (SNPs and indels) are associated with obesity, insulin resistance, type 2 diabetes mellitus, and metabolic syndrome." (PMID 25495519, 2014). "Further studies are still needed to elucidate the functional effects of the UCP3-55C/T polymorphism on UCP3 expression as well as to confirm its association with obesity." (PMID 24804925, 2014). "Variants of UCP2 and UCP3 genes have been reported to be associated with obesity, but the available data on the relationship are inconsistent." (PMID 23560041, 2013). "Characteristics of the UCP3 -55C/T polymorphism allelic and genotype distribution for obesity risk in studies included in the meta-analysis." (PMID 23560041, 2013). "Pooled measures for the association between the UCP2–866G/A, Ala55Val and UCP3–55C/T polymorphisms and susceptibility to obesity." (PMID 23560041, 2013). "ADIPOQ rs2241766 showed a nominal significant association with overall obesity (OR 2.34, Prec = 0.033, recessive model), and UCP3 rs1800849 was significantly associated only with class I/II obesity (OR 1.33, Padd = 0.050, additive model)." (PMID 23950976, 2013). "In this population, only 2 of the 8 (25%) biological candidate genes (ADIPOQ and UCP3) were associated with obesity, although only ADIPOQ remained significant after adjusting for admixture." (PMID 23950976, 2013). "Difference in UCP3 exon 5 variants have been observed between African and white American women and suggested a role of UCP3 for the higher predisposition of obesity in African American women." (PMID 22087257, 2011).
Obesity (continued). "Variants of the SIRT1, SIRT2, SIRT6, UCP1, UCP2, and UCP3 genes have been related to diabetes, obesity, serum high-density lipoprotein cholesterol (HDL), and inflammation." (PMID 22087257, 2011). "A review of human genetic studies examining expression of UCP2 or UCP3 and the propensity to obesity suggested that some obesity related phenotypes are significantly associated with these UCPs." (PMID 16968550, 2006). "However, alternative studies associated the C/T genotype with lower UCP3 mRNA levels and a reduced risk of obesity." (PMID 41300761, 2025). "Thus, evidencing and observed degree of concordance of a UCP3 variants with an obesity in a cohort of children from Central Brazil." (PMID 36810017, 2023). "This review covers the main Ucp SNPs A–3826G, A–1766G, A–112C, Met229Leu, Ala64Thr (Ucp1), Ala55Val, G–866A (Ucp2), and C–55 T (Ucp3), which may be associated with the development of obesity, disturbance in lipid metabolism, T2D, and cardiovascular diseases." (PMID 32450815, 2020). "The Ucp1 homologues, such as Ucp2 and Ucp3 also deserve attention among candidate genes whose polymorphisms may be associated with obesity and risk factors for cardiovascular diseases." (PMID 32450815, 2020). "Interestingly, elevated UCP3 levels were observed in obesity-resistant mice and a decrease in UCP3 levels was associated with insulin sensitivity, a condition that precedes diabetes." (PMID 30295819, 2018). "We confirmed UCP3 gene transcription is initiated by 1,25(OH)2D3 (calcitriol)/VDR binding to the UCP3 promoter on the molecular basis, which reinforces energy metabolism, resulting in resistance to obesity caused by a high fat diet, as dealt with in this paper." (PMID 27473111, 2016). "Leucine supplementation also could decreased diet-induced obesity by increasing resting energy expenditure associated with increased uncoupling protein 3 (UCP3) expression in thermo-genic tissues in mice." (PMID 26593945, 2015). "A meta-analysis was performed to determine whether there are any associations between the UCP2 -866G/A, Ala55Val, and UCP3 -55C/T polymorphisms and obesity susceptibility." (PMID 23560041, 2013). "UCP2 and UCP3 genes cluster on chromosome 11q13 in a region linked to lower resting metabolic rate in humans, which is also syntenic to a region of mouse chromosome 7 linked to hyperinsulinemia and obesity." (PMID 22216339, 2011). "The promoter area variant alleles in UCP2 (rs659366-A) and in UCP3 (rs1800849-T) have been shown to increase gene expression, and thus these alleles might protect against obesity." (PMID 19769793, 2009). "In the present study we evaluated whether the UCP2 and UCP3 genes act as modifiers for obesity and diabetes related risk factors." (PMID 19769793, 2009). "To test whether departure from HWE is specific to CART, we reanalyzed previous genotyping data obtained in the 368 controls for eight genes, some of them associated with obesity or associated phenotypes such as UCP3, APM1, PGC1 and GAD2 genes." (PMID 15823203, 2005). "It is worth noting that a previous meta-analysis from our group showed an association of the UCP3-55C/T polymorphism with risk for type 2 diabetes mellitus in Asians (OR = 1.22, 95% CI 1.04–1.44, allele contrast model), further indicating a role for this polymorphism in obesity-related features." (PMID 24804925, 2014). "However, the impact of UCP2 and UCP3 polymorphisms on obesity susceptibility is still under debate." (PMID 23560041, 2013). "However, the impact of UCP2 and UCP3 polymorphisms on obesity is still under debate." (PMID 23560041, 2013). "This narrative review examined the functional and clinical significance of UCP3 and PCSK1 variants in severe obesity, presenting two case reports to illustrate their potential impact." (PMID 40281302, 2025). "Our review highlights the potential clinical relevance of rare, functionally significant variants in UCP3 and PCSK1 in patients with severe obesity." (PMID 40281302, 2025).
Obesity (continued). "This review aimed to explore the emerging role of rare genetic variants in UCP3 and PCSK1 in non-syndromic obesity." (PMID 40281302, 2025). "We recommend that functional validation and exploring variant-variant interactions within relevant genes such as UCP3 and PCSK1 will be critical to improving our understanding of monogenic (rare) obesity and refining personalized treatment strategies." (PMID 40281302, 2025). "Although UCP3 and PCSK1 have been extensively studied, the phenotypic impact of their combined variants on obesity remains less explored." (PMID 40281302, 2025). "Promoting metabolic inefficiency in skeletal muscle by UCP1 or UCP3 overexpression can increase metabolic rate and prevent diet-induced obesity." (PMID 37249575, 2023). "A study evaluating the role of UCP-2 and UCP-3 in obesity found that the overexpression of UCP-2 and/or UCP-3 resulted in a decrease in fat mass with an increase in LDL cholesterol in mice, thus highlighting the role of UCPs in alleviating obesity." (PMID 36900198, 2023). "Pancreatic beta cells also express UCP3, linking its role to energy expenditure, glucose metabolism, diabetes, and obesity." (PMID 35323702, 2022). "Overexpression of UCP1 and UCP3 in brown adipose tissue and skeletal muscle appears to mimic endurance training and prevent the development of obesity in female mice by reducing triglyceride accumulation." (PMID 36009191, 2022). "The effect of the rs1800849 of the UCP3 gene on BMI and obesity is still being discussed, as there are conflicting research results." (PMID 36140780, 2022). "Research in obesity and diabetic mouse models has demonstrated that leptin and serum levels of FFAs play an essential role in regulating UCP3 expression in skeletal muscle, and that muscle thermogenesis in these models is impaired." (PMID 35323702, 2022). "The role of the UCP3 gene in the development of T2D and obesity has been intensively studied, and several UCP3 gene polymorphisms have been reported to be associated with T2D." (PMID 36009191, 2022). "Experimental evidence from multiple studies have proposed UCP3 as a modulator of energy metabolism and a possible protective role in obesity." (PMID 34829617, 2021). "This is consistent with data showing either unchanged or decreased cardiac UCP3 levels in genetic models of obesity, despite increased mitochondrial uncoupling." (PMID 32493392, 2020). "Recent research reported that muscle mitochondrial-related genes, including NRF1, PGC1α, and UCP3, regulate insulin resistance during obesity." (PMID 32041272, 2020). "Our results highlight pronounced age-dependent differences in the expression of UCP1 and UCP3 that is especially important in the pathogenesis of obesity, diabetes, and cardiovascular diseases." (PMID 31806023, 2019). "Understanding the regulation mechanism of UCP1/UCP3 and their exact role within the mitochondria inner membrane will provide new strategies to treat obesity and its related diseases." (PMID 31806023, 2019). "UCP1 homologues, i.e., UCP2 and UCP3, have similar roles and are potential therapeutic target molecules against obesity." (PMID 31312229, 2019). "We found that UCP3 protein levels were systematically decreased in the hearts of mouse and rat models of obesity, insulin resistance and type 2 diabetes." (PMID 30374710, 2018). "The goals of this study were to reexamine myocardial UCP3 expression in several rodent models of obesity, insulin resistance and type 2 diabetes, and to determine the consequences for cardiac adaptation to I/R." (PMID 30374710, 2018). "In the present study, we extended our investigations to monogenic rodent models of obesity, insulin resistance and type 2 diabetes and found that cardiac UCP3 protein levels were reduced between 20% and 49%." (PMID 30374710, 2018). "Cardiac UCP3 content was decreased by 20% in two of the most widely used models of obesity and type 2 diabetes, the ob/ob and db/db mice." (PMID 30374710, 2018).
Obesity (continued). "In this review we will give a general description of biochemical and molecular characteristics of UCPs and then we will discuss the role of UCP2 and UCP3 in cell death and heart failure in metabolic disease such as obesity." (PMID 27642497, 2016). "The early stage of heart failure in obesity is characterized by an overexpression of UCP2 or UCP3 in response to increased FFA and mitochondrial ROS generation and induced mild uncoupling of oxidative phosphorylation without affecting ATP level." (PMID 27642497, 2016). "UCP3 is negatively correlated with body mass index (BMI), suggesting a potential link between UCP3 and obesity, potentially by the proposed roles of UCP3 in facilitating fatty acid oxidation and preventing triglyceride accumulation." (PMID 27473111, 2016). "The involvement of UCP3 in protection from ROS-induced oxidative stress and in fatty acid oxidation rate enhancement suggests a protective role for this protein in obesity." (PMID 26959981, 2016). "Overexpression of UCP3 mRNA in mouse skeletal muscle reduces diet-induced obesity, suggesting that UCP3 has therapeutic potential in the treatment of obesity." (PMID 27473111, 2016). "For these reasons, UCP2 and UCP3 can be important targets for the treatment of aging, degenerative diseases, diabetes and, perhaps, obesity." (PMID 24796298, 2014). "Uncoupling protein 1, UCP2 and UCP3 are candidate genes for obesity because they decrease mitochondrial membrane potential and mediate proton leak." (PMID 24804925, 2014). "Recently, numerous studies have examined the associations between the three common variants in the UCP2-UCP3 gene cluster and diabetes or obesity risk, including UCP2 -866 G/A, Ala55Val C/T and UCP3 -55 C/T polymorphism." (PMID 23560041, 2013). "Uncoupling protein 1, UCP2 and UCP3 are regarded as candidate genes for obesity and T2DM because they have been found to decrease mitochondrial membrane potential and mediate proton leak." (PMID 23365654, 2013). "Twelve studies examined the association between the UCP2 -866G/A polymorphism and obesity risk, nine studies for the UCP2 Ala55Val polymorphism and eight for the UCP3 -55C/T polymorphism." (PMID 23560041, 2013). "Activation and elevation of PPARα and PPARδ expression is known to increase expression of CPT1, ACO and UCP3 to elevate energy expenditure, subsequently resulting in anti-obesity actions." (PMID 21799697, 2011). "While mounting evidence has documented the importance of both UCP2 and UCP3 variability in the pathophysiology of different chronic metabolic diseases, such as diabetes and obesity, relatively little is known of their implication in human aging and longevity." (PMID 22216339, 2011). "Enhanced expressions of both UCP3 and PDK4 in skeletal muscle have been associated with obesity and type II diabetes in humans." (PMID 19787081, 2008). "Ucp3 is also induced by higher levels of intramuscular nonesterified fatty acids, which are associated with obesity." (PMID 40847538, 2025). "As the loci of UCP2 and UCP3 genes on mouse chromosome 7 and human chromosome 11 are close, they represent good candidate genes for the quantitative trait locus of diet-induced obesity and diabetes." (PMID 35323702, 2022). "It is reported that exercise-induced apelin in mothers activates sarcolipin and uncoupling protein 3 (UCP3) in the muscles of children and protects them from obesity because Sarcolipin and UCP3 regulate thermogenesis in muscles to improve metabolic homeostasis." (PMID 36093083, 2022). "UCP3 plays an active role in ROS production and fatty acid oxidation, which makes it a candidate for better understanding the pathophysiology of metabolic disorders such as obesity and type 2 diabetes mellitus." (PMID 34829617, 2021). "D11S912 and other STRs flanking UCP2 and UCP3 showed some evidence of linkage with obesity and BMI." (PMID 28615046, 2017).